MIR27A (microRNA 27a)
Synonyms: hsa-mir-27a; MIR27; MIRN27A; mir-27a
Safety:
Unwanted effects reported when the protein is acted on. In parentheses: how it was acted on, where the effect was seen, and who reports it.
severe toxicity (source: ClinPGx)
Gene: MicroRNA gene on chromosome 19 (13,836,440 to 13,836,517, reverse strand). Ensembl gene ENSG00000207808.
Pathways (Reactome):
Gene expression (Transcription): RUNX1 regulates genes involved in megakaryocyte differentiation and platelet function
Gene Ontology:
Cellular component: RISC complex
Homologues: Orthologues: chimpanzee ptr-mir-27a (100% identical), macaque mml-mir-27a (100% identical), mouse Mir27a (95% identical), pig ssc-mir-27a (90% identical), guinea pig MIR27A (88% identical), dog MIR27A (76% identical), tropical clawed frog xtr-mir-27a (74% identical), zebrafish mir27a (69% identical), zebrafish mir27c (63% identical). Paralogues in human: MIR27B (65% identical).
Diseases named in the same sentence as MIR27A in open-access papers:
MIR27A is named in the same sentence as 4 diseases in open-access papers, as found by Europe PMC text mining. Sharing a sentence is not in itself a finding about the gene and the disease. The quoted sentences say what the papers report.
hepatoma (1 paper, 2016). "MIR-27a was described to be involved in lipid metabolism, by regulating RXRα, PPARα/γ, FASN, SREBP1, SREBP2, and was able to inhibit HCV replication in human hepatoma cells." (PMID 26728044, 2016).
Insulin resistance (1 paper, 2025). Increased resistance towards insulin, that is, diminished effectiveness of insulin in reducing blood glucose levels. "Similarly, the MIR-27A gene, linked to insulin resistance and hepatic lipid metabolism, was hypermethylated, predisposing these animals to the perturbed metabolic phenotype." (PMID 40914344, 2025).
tumor (1 paper, 2015). "Our results provide evidence, for the first time, that CBFA2T3 acts as a tumor suppressor in OS development and progression and can be post-transcriptionally regulated by the pro-metastatic MIR-27a gene." (PMID 25749032, 2015).
MIR27A also shares sentences with these, for which no sentence is quoted: Obesity (1 paper).